MITF (melanocyte inducing transcription factor)
Diseases named in the same sentence as MITF in open-access papers (continued):
Sharing a sentence is not in itself a finding about the gene and the disease.
melanoma (continued). "It is known that MITF is closely linked to cell cycle progression in malignant melanoma growth." (PMID 28880216, 2017). "Moreover, MC1R and MITF, other than being moderate-penetrance melanoma susceptibility genes, play an important role in the pigmentation of skin and hairs." (PMID 27776349, 2017). "In melanoma and derived daughter cell lines, overexpressed glycodelin also shows a strongly positive correlation with microphthalmia-associated transcription factor (MITF) expression, a key regulatory gene in melanoma oncogenesis and progression." (PMID 29238349, 2017). "Lineage associated transcription factors include MITF for the melanoma cell line SK-MEL-5, TP63 for the lung cancer line A549, KLF5 for the colon cancer line HT-29, and ETS family transcription factors for prostate, colon, ovarian, and breast cancer cell lines." (PMID 28854983, 2017). "The results confirm that TFAP2A frequently co-occupies regulatory elements with MITF, identify genes underlying pigmentation phenotypes in model organisms and patients with TFAP2A mutations, and reveal TFAP2A as a candidate locus to modify diseases associated with MITF, including melanoma." (PMID 28249010, 2017). "Recent studies have indicated the cooperation between the PPAR family and the melanocyte-stimulating hormone receptor (MC1R)-microphthalmia-associated transcription factor (MITF) signaling pathway, which resulted in enhanced melanogenesis in melanocytes and melanoma cells." (PMID 29145845, 2017). "Melanin synthesis is a unique characteristic of melanoma and a complex process involving microphthalmia-associated transcription factor (MITF), a transcription factor and a master regulator of melanogenesis, whose expression itself is activated by the MAPK signaling." (PMID 29187213, 2017). "In many melanomas, PGC1α expression is low due to suppression of MITF by oncogenic BRAF mutations." (PMID 29137417, 2017). "To assess whether there was a causal link between glucose-mediated MITF expression and glucose-dependent growth in melanoma cells, we ectopically expressed MITF from the cytomegalovirus (CMV) promoter, which was not affected by glucose levels." (PMID 28380427, 2017). "We also assessed the MITF phenotype of the cell lines and short-term melanoma cell cultures, as either high or low expression of this transcription factor has been associated with drug resistance in melanoma." (PMID 26678033, 2016). "To test whether the melanoma phenotypes are associated with different transcript transformations during tumor progression, we studied the MITF+ and MITF– sets independently to derive signatures of survival." (PMID 27535130, 2016). "Taken together, SOX5, SOX10 and MITF seem to have a crucial clinical impact and our developed linear regression based expression signature of these three genes associated in particular with melanomas with a small Breslow thickness." (PMID 26927636, 2016). "Melanoma differs from other cancers by its ability to produce the pigment melanin via melanogenesis; this biosynthesis is essentially regulated by microphthalmia-associated transcription factor (MITF)." (PMID 26927636, 2016). "The ability of WNT5A to inhibit MITF, a downstream target of β-catenin, may be one cause of resistance in BRAFi-treated melanoma patients, as MITF depletion can activate EGFR signaling, which can confer BRAFi resistance." (PMID 26393652, 2015). "In this review, we discuss the complexity of a multilevel regulation of MITF expression and activity that underlies distinct context-related phenotypes of melanoma and might explain diverse responses of melanoma patients to currently used therapeutics." (PMID 25433395, 2015). "With loss of NF1 and more recently an increase of CDK2 (in association with MITF) in melanomas being involved in the resistance to BRAF-inhibitor (BRAFi) therapy, we next sought to investigate whether miR-514a might be involved in this process." (PMID 25980496, 2015).
melanoma (continued). "BRG1 may be increased during melanoma progression, potentially causing a shift of MITF target genes towards anti-apoptotic signaling via BIRC7/ML-IAP, although conflicting reports exist about BRG1 expression in melanoma progression." (PMID 26426052, 2015). "In addition, an activating frameshift or non-sense mutations in SOX10 have been identified in melanoma cells, and MITF and SOX10 have been found mutated in a mutually exclusive manner." (PMID 25433395, 2015). "To address the global relevance of c-Jun induction in the context of MITF loss for inflammatory hyperresponsiveness of melanoma cells, we performed co-knockdown experiments with siRNAs against MITF and c-JUN in the absence or presence of TNF-α and analysed the transcriptional changes by microarray." (PMID 26530832, 2015). "A subpopulation of melanoma cells expresses the melanocyte lineage-specific transcription factor MITF (microphthalmia-associated transcription factor), which upregulates PGC-1α, resulting in mitochondrial biogenesis increase and therefore rendering cells addicted to mitochondrial activity." (PMID 26713093, 2015). "Although genetic alterations, including mutations and amplification of MITF, are found in melanoma samples, fluctuating MITF activity in melanoma cells is rather due to microenvironmental cues, critical epigenetic states and modifications of upstream signaling pathways." (PMID 25433395, 2015). "We show that MITF associates the NURF chromatin-remodelling factor in melanoma cells." (PMID 26440048, 2015). "Interestingly, a mutation in TRRAP has recently been associated with human melanoma that together with its interaction with MITF suggests a role in melanomagenesis." (PMID 25803486, 2015). "A study of XN on melanogenesis using B16 melanoma cells showed that XN might act as a hypo-pigmenting agent through the down regulation of microphthalmia-associated transcription factor (MITF) in the cAMP-dependent melanogenic pathway." (PMID 25574819, 2015). "We show that MITF associates with the NURF chromatin-remodelling factor in melanoma cells." (PMID 26440048, 2015). "Additionally, the quantification of these variants in a panel of 86 melanoma samples revealed the apparently increased expression of MITF(−) in metastatic melanomas." (PMID 25433395, 2015). "Downregulation of MITF has been positively linked with melanoma cell migration and invasion." (PMID 26393652, 2015). "MITF itself is the target of a mutation that favors melanoma development." (PMID 25105565, 2014). "USP13 is essential for melanoma growth in vitro and in vivo and might be another target in MITF-mutated melanoma." (PMID 24743024, 2014). "Indeed, genomic amplification of MITF associated with a decreased five-year survival and germline mutation that predisposes carriers to melanoma were reported." (PMID 24742694, 2014). "We recently identified four molecular subtypes of melanoma tumours using gene expression profiling characterized by differential expression of immune response genes, microphthalmia-associated transcription factor (MITF)-regulated genes and proliferation-related genes." (PMID 24399611, 2014). "Resveratrol at 15 μM could downregulate α-MSH stimulated cancer stem cell-associated molecules (Wnt-1, β-catenin and MITF expression) in melanoma B16 cells and finally decreased the cell proliferation, migration, and differentiation." (PMID 24325567, 2013).
melanoma (continued). "MITF is also an amplified or mutated oncogene in a fraction of melanomas, where it modulates pathways central to survival, metabolism, and differentiated state (i.e., melanoma subtype)." (PMID 24157419, 2013). "Interestingly, one of these genes, MITF has recently been reported to be involved later on in adulthood in melanoma susceptibility and invasion." (PMID 23796690, 2013). "In particular Wnt5A, which has been associated with enhanced invasiveness in melanoma was predominantly down-regulated in the B compared with the A class and conversely, MITF and melanoma differentiation antigens were prevalently expressed by the B class melanomas." (PMID 22537248, 2012). "MITF has been recently identified as a novel intermediate risk melanoma-predisposing gene." (PMID 22978401, 2012). "CDK4, a melanoma susceptibility gene, has also been shown to be a target of MITF." (PMID 22848417, 2012). "Senescence-like phenotypes including proliferation arrest were induced in melanoma cells by the inhibition of oncogenic chromatin-remodeling factor DEK or microphthalmia-associated transcription factor MITF, a master regulator of melanocyte homeostasis and melanomagenesis." (PMID 23249808, 2012). "Microphthalmia-associated transcription factor (MITF) as one important transcriptional target of β-catenin in melanoma cells could be critically involved in survival and proliferation of metastatic melanoma cells with high β-catenin transcriptional activity." (PMID 21858114, 2011). "The MITF gene, encoding a basic-helix-loop-helix-leucine zipper transcription factor, is expressed in melanocytes, retinal pigmented epithelium, mast cells, osteoclasts, and melanoma." (PMID 22046555, 2011). "Therefore, we selected MITF as a cancer-associated molecule in melanoma and introduce recent findings regarding MITF in this paper." (PMID 22046555, 2011). "However, MITF expression has been associated with both poor prognosis as well as better prognosis of melanoma, depending on the stage of the tumor." (PMID 22545195, 2010). "Recently it was reported that the MiTF pathway was also frequently mutated in human melanomas." (PMID 20701798, 2010). "Importantly, we show that BRN2 and MITF expression are strongly correlated with the presence of BRAF mutations in human melanoma samples." (PMID 18628967, 2008). "Furthermore, depletion of endogenous BRN2 reduced the levels of endogenous MITF protein in all melanoma cell lines in which BRAF is mutated." (PMID 18628967, 2008). "Additionally, BRAF mutation (V600E) suppresses MITF and PGC1α expression in melanoma cells." (PMID 38774408, 2024). "In addition, we found a MITF gene PV in patient A759, a gene associated with melanoma development." (PMID 39519399, 2024). "Melanoma dedifferentiation is a gradual process that entails a loss of melanocytic antigens and a gain of neural crest markers and can occur through reduced expression of the microphthalmia associated transcription factor (MITF), a key regulator of the melanocytic lineage." (PMID 39736644, 2024). "Additionally, using published H3K27ac ChIP-Seq data, we identified this super-enhancer in the MITF-low metastatic melanoma cell lines (SKmel147, A375, and LOX IMVI) and found loss of H3K27ac in the MITF-high metastatic melanoma cell lines (501MEL, SKmel2, SKmel5, and SKmel239)." (PMID 38319712, 2024). "Interestingly, the sole patient found to be a “double carrier” of the POT1 and MITF variants had an extremely high recurrence rate of melanoma (reporting 10 different resections over the years), possibly reflecting an additive/synergistic effect of the two variants." (PMID 38540414, 2024). "Moreover, modulation of MC1R downstream signaling is likely to depend on the mutational landscape of melanoma cells, and melanocyte-specific responses such as regulation of MITF levels cannot be properly analyzed in heterologous cells engineered to express specific MC1R forms." (PMID 37762683, 2023).
melanoma (continued). "However, whether the lysoSM-induced loss of MITF is associated with the reactivation of neural crest progenitor genes and melanoma progression is unknown." (PMID 36230781, 2022). "However, the expression of TRP2 was similar between the normal and melanoma condition, which may be caused by the indirect transactivation of MITF on the TRP2 gene promoter." (PMID 36499416, 2022). "Thus, a loss of MITF not only correlated with treatment resistance but also melanoma metastasis." (PMID 35740696, 2022). "Importantly, immunohistochemical analyses of primary and metastatic melanoma patient samples in a tissue microarray, showed that molecular markers of collagen levels were associated with the transcriptomic signature for melanoma cell phenotypic dedifferentiation via the YAP/PAX3/MITF axis." (PMID 36119516, 2022). "Moreover, one study suggested that higher MITF levels in melanoma cells might be associated with the repression of ECM and focal adhesion genes." (PMID 36119516, 2022). "Furthermore, CREB and MITF have been implicated in melanoma tumor growth and metastasis." (PMID 34134626, 2021). "Also, loss of MITF increased stem cell marker SOX2 that is important in melanoma cell self-renewal." (PMID 35127523, 2021). "In the case of MITF, we observe that among the 2,372 individuals with the lowest dominant effect scores (comprising 0.9% of the cohort), 61 (2.57% of that group) have had melanoma, compared to only 1.12% risk of melanoma in the rest of the cohort (leading to observed risk-ratio of 2.3)." (PMID 34290314, 2021). "In addition to melanoma, germline mutations of MITF have been associated with other malignancies." (PMID 34442055, 2021). "Additionally, MITF has been proposed as a diagnostic marker for melanoma." (PMID 34641584, 2021). "Therefore, they proposed that MITF might have a role in conferring a genetic predisposition to co-occurring melanoma and RCC." (PMID 34289891, 2021). "In melanoma, MITF has been observed to be both up and downregulated, and the downregulation of MITF is associated with a more metastatic and treatment-resistant phenotype, suggesting an MITF-driven oxidative phenotype might be easier to treat in certain states of cancer progression." (PMID 34831420, 2021). "Moreover, meta-analysis of gene expression profiling of hundreds of human melanoma cells identified a highly invasive phenotype, characterized by extremely low MITF expression, associated with a stemness- and epithelial-to-mesenchymal transition (EMT)-based gene expression signature." (PMID 33121001, 2020). "Furthermore, drug-resistant melanoma cells can dedifferentiate to different extent that is associated with loss of melanoma-specific transcription factor, MITF, and several studies have suggested that the dedifferentiation status can dictate sensitivity of cancer cells to ferroptosis." (PMID 32340261, 2020). "Another feature of melanoma tumors that may affect the capacity of escaping T-cell recognition is melanoma cell dedifferentiation characterized by decreased expression of the microphtalmia-associated transcription factor (MITF) gene." (PMID 32245160, 2020). "In cases of familial melanoma, testing for the MITF mutation may be helpful." (PMID 32429485, 2020). "The melanoma cells oscillate between two interchangeable phenotypes using microphthalmia-associated transcription factor (MITF)-rheostat signaling, namely, the proliferative state with high levels of MITF expression (MITFhi) or invasive phenotype with low levels of MITF (MITFlow)." (PMID 33329751, 2020).
melanoma (continued). "Although previous studies considered AM as de-differentiated or poorly differentiated melanoma, AM cells maintain the melanocytic lineage and melanin-forming ability, which is demonstrated by tyrosinase and microphthalmia-associated transcription factor (MITF) expression." (PMID 32825562, 2020). "Indeed, differential expression of MITF variants appears to influence phenotype, tumor biology and growth characteristics, allowing the identification of subgroups with different prognosis within melanoma patients." (PMID 32244895, 2020). "Therefore, it is thought that melanoma cells have the possibility to shift between different transcriptional programs mostly depending on the oscillation of the microphthalmia-associated transcription factor MITF." (PMID 33202944, 2020). "The importance of canonical WNT-signaling in melanoma initiation is mostly associated with β-catenin ability to regulate the expression of a wide range of genes of the melanocyte lineage, and its involvement in regulation of proliferation is most likely related to the activation of MITF expression." (PMID 32659938, 2020). "Thus it is possible that TDG knockdown causes senescence in melanoma cells by decreasing the levels and activity of p300 and MITF, which in turn may further deplete TDG by reducing its transcription." (PMID 30674989, 2019). "Thus, we considered individual melanoma phenotypes linked to distinct MITF expression levels." (PMID 30277012, 2019). "All differences in the composition of subpopulations, namely NGFR-positive, MITF-positive and Ki-67-positive cells observed in this study between normoxia and hyperoxia, were cell-line specific but also point at oxygen as the causative factor of melanoma heterogeneity." (PMID 31461993, 2019). "Thus, high proliferation signatures of high grade melanomas (late PT cells) may be associated with high, intermediate or low pigmentation signatures and MITF signatures, suggesting overlapping but also individual patterns of tumor progression." (PMID 29614062, 2018). "In addition, mechanisms of primary treatment resistance of BRAF-mutant melanoma cells may be due to a MITF low/NF-κB high phenotype, which could be linked to a specific gene expression profile." (PMID 27903987, 2017). "Furthermore, although exogenous MITF causes a p21CIP1‐dependent cell cycle arrest in mouse fibroblasts and is a bona fide MITF target gene in melanoma cells, cAMP – despite upregulating MITF – does not provoke an increase in p21CIP1 expression in melanoma cells." (PMID 25818589, 2015). "Thus, BRM might become a crucial remaining ATPase maintaining the expression of MITF and perhaps additional new targets described here in melanoma cells in vivo under conditions of BRG1 loss, especially in later stages of tumor progression." (PMID 23349796, 2013).